APOA5 (apolipoprotein A5)
Diseases named in the same sentence as APOA5 in open-access papers (continued):
Sharing a sentence is not in itself a finding about the gene and the disease.
Sepsis (continued). "Furthermore, serum ApoA5 levels on PICU admission in pediatric population with sepsis were significantly higher than those in the healthy children." (PMID 32322166, 2020). "Importantly, an AUC of serum ApoA5 for discriminating sepsis from control was 0.753 with a 95% CI of 0.654-0.852." (PMID 32322166, 2020). "Moreover, the findings of the present study suggest a prognostic value of ApoA5 in children with sepsis, and further studies are needed to confirm this conclusion in a well-designed prospective study with a large population." (PMID 32322166, 2020). "Moreover, the findings of the present study suggest a prognostic value of ApoA5 in children with sepsis, and lower serum ApoA5 than 822 ng/mL predicts worse outcome in pediatric sepsis." (PMID 32322166, 2020). "However, the role of serum apolipoprotein A-V (ApoA5) in sepsis is poorly understood in pediatric patients." (PMID 32322166, 2020). "However, little is known about the role of ApoA5 in pediatric patients with sepsis." (PMID 32322166, 2020). "Therefore, the aim of this study was to evaluate whether serum ApoA5 levels on PICU admission were correlated with the prognosis in children with a clinical diagnosis of sepsis/septic shock." (PMID 32322166, 2020). "Though both achieved similar AUC, sensitivity and specificity, ApoA5 focuses on ICU mortality of paediatric patients, and HSPA12B focuses on 28-day mortality of patients with severe sepsis." (PMID 37456011, 2023). "During sepsis, the serum concentrations of some proteins, such as pancreatic stone protein (PSP), copeptin, and APOA5, have been observed to increase." (PMID 36755189, 2023). "The biomarkers, ApoA5 and HSPA12B, which were the only two biomarkers reported their clinical performance, demonstrated consistent significant changes in mouse sepsis with human sepsis." (PMID 37456011, 2023). "The receiver operating characteristic revealed that the area under the curve (AUC) for APOA5, copeptin, and PSP (0.965, 0.960, and 0.868, respectively) demonstrated high sensitivity (96%, 94%, and 80%) for sepsis diagnosis." (PMID 36755189, 2023). "ROC curve analysis showed that APOA5, CRP, copeptin, and PSP predicted pediatric sepsis with high sensitivity." (PMID 36755189, 2023). "In the present study, our findings show that serum ApoA5 levels in nonsurvivors were significantly lower than those in survivors with sepsis." (PMID 32322166, 2020). "Serum ApoA5 levels on PICU admission were significantly lower in nonsurvivors with sepsis compared with survivors (P = 0.009)." (PMID 32322166, 2020). "Given the complexity of infection in the PICU, the stability of serum ApoA5 levels suggested that ApoA5 might be a general biomarker for adaptive response regardless of source of infection during sepsis." (PMID 32322166, 2020). "Serum ApoA5 levels were significantly low in nonsurvivors with sepsis." (PMID 32322166, 2020).
central obesity (3 papers, 2013 to 2022). "An interesting finding in our study was the strong sex interaction (P = 0.004) observed with the development from normal to abdominal obesity where the G-allele in the rs964184 (ZNF259/APOA5) revealed a risk effect in males while the opposite was the case in females." (PMID 26445370, 2015). "APOA5 rs662799 and rs2075291 carriers are known to have increased plasma triglyceride, and our recent study showed correlation of APOA5 rs662799 with central obesity in males." (PMID 23829168, 2013).
coronary atherosclerosis (3 papers, 2009 to 2025). Atherosclerosis of the coronary vasculature. "SNPs in APOA5 are also associated with plasma apo A-I level, severity of coronary atherosclerosis as well as its progression." (PMID 19878569, 2009). "Thus, the findings further substantiate the clinical significance of APOA5 variants in coronary atherosclerosis." (PMID 19878569, 2009). "However, the findings regarding the associations of the S19W SNP with the severity and progression of coronary atherosclerosis are new and in harmony with the effects of the APOA5 variants on plasma HDL-C, apo A-I and triglyceride levels." (PMID 19878569, 2009). "Likewise, the APOA5 variant was also associated with the severity of coronary atherosclerosis at the baseline as well as progression of coronary atherosclerosis over a 2.5 years period." (PMID 19878569, 2009). "An interesting finding was the concordant association of the S19W SNP in APOA5 with plasma HDL-C and apo A-I levels as well as the severity of coronary atherosclerosis and its progression." (PMID 19878569, 2009). "The non-synonymous S19W SNP in APOA5 is also an independent determinant of plasma apo A-I level, severity of coronary atherosclerosis and its progression." (PMID 19878569, 2009).
carotid atherosclerosis (2 papers, 2021 to 2025). A thickening and loss of elasticity of the walls of carotid arteries that occur with formation of atherosclerotic plaques. "In this study, the analysis of the ZPR1, APOA5, and GCKR genes in patients with SLE, showed that GCKR rs1260326 is strongly related to the presence of carotid atherosclerosis." (PMID 34065555, 2021).
Chronic Hepatitis B (2 papers, 2017 to 2019). "Serum apolipoprotein C3 (ApoC3) and apolipoprotein A5 (ApoA5) levels were decreased in chronic hepatitis B (CHB) patients, however the relationship between ApoC3 or ApoA5 and HBV DNA load remains elusive." (PMID 31186008, 2019).
Combined hyperlipidemia (2 papers, 2014 to 2022). "The second model showed that HT patients carrying the APOA5 p.19W allele exhibit an increased risk of presenting mixed hyperlipidemia (OR = 8.8; 95% CI: 1.76–44.0; P = 0.02) under the recessive model (WW v." (PMID 25587205, 2014).
COVID-19 (2 papers, 2022 to 2023). A disease caused by infection with severe acute respiratory syndrome coronavirus 2. "APOA5 has been described to be differentially regulated in severe COVID-19 compared to healthy controls and also during recovery from this condition." (PMID 37293294, 2023).
depression (2 papers, 2024 to 2025). "A comparison of plasma protein expression between patients with depression and healthy controls has revealed that differentially expressed proteins, including apolipoproteins such as the APOE, APOC4, and APOA5, lead to significant alterations of lipid and metabolic functions." (PMID 39062058, 2024).
familial hypertriglyceridemia (2 papers, 2020 to 2024). "As a component of high-density lipoprotein, APOA5 is also associated with lipid-related diseases such as hypertriglyceridemia 1 and hyperlipoproteinemia type V." (PMID 39050255, 2024). "APOA5 (Apolipoprotein A5) is a protein-coding gene and linked disorders were hyperlipoproteinemia Type V and familial hypertriglyceridemia, lipoprotein metabolism, and lipid signaling pathway." (PMID 33339179, 2020).
Hyperglycemia (2 papers, 2022 to 2024). An increased concentration of glucose in the blood. "Notably, individuals with higher serum ApoA5 levels were more likely to suffer from hyperglycemia (P=0.046)." (PMID 35854768, 2022). "Moreover, individuals with higher serum ApoA5 levels were also more likely to suffer from hyperglycemia." (PMID 35854768, 2022). "The individuals with hyperglycemia tend to have a higher ApoA5 level, but the difference was not statistically significant (29.4 ± 4.8 vs. 28.6 ± 4.6 μg/mL, P=0.075)." (PMID 35854768, 2022).
Hyperinsulinemia (2 papers, 2013 to 2018). An increased concentration of insulin in the blood. "SNP -1131T>C is located in the proximal promoter of the APOA5 gene and is associated with elevated TG levels and hyperinsulinemia." (PMID 23970179, 2013).
liver failure (2 papers, 2017 to 2019). A liver disease characterized by the liver losing or has lost all of its function. "However, LPS induced liver injury in a dose-dependent pattern even if the mice were injected with 20 μg pEGF-N1-ApoA5, which demonstrated the fact that ApoA5 exhibited the protective effect against LPS/d-GalN-induced mice liver failure within a certain range." (PMID 31077206, 2019). "Thus in present study, we established a mouse model of FHF with LPS and d-GalN, aiming to investigate the therapeutic effect of ApoA5 in liver failure." (PMID 31077206, 2019). "In summary, this study demonstrated that ApoA5 had a protective effect against LPS/d-GalN-induced liver failure within a certain range by inhibiting TLR4-mediated NF-κB pathway, and ApoA5 might be a potential target for the prevention of FHF induced by LPS/d-GalN in mice." (PMID 31077206, 2019).
schizophrenia (2 papers, 2022 to 2024). A major psychotic disorder characterized by abnormalities in the perception or expression of reality. "Considering the relevant changes in schizophrenia patients, we have evaluated the relative parameters and apoA5 expression in a mouse model fed with olanzapine." (PMID 36034782, 2022). "Further, reduction of plasma apoA5 levels was observed in schizophrenia patients and mice after short-term treatment of olanzapine." (PMID 36034782, 2022). "Thus, olanzapine-induced disturbance of intracellular trafficking and secretion of apoA5 potentially contributes to the development of NAFLD in schizophrenia patients, which had been verified in olanzapine-treated mice and supported by other studies." (PMID 36034782, 2022).
amyloidosis (1 paper, 2016). A disorder characterized by the localized or diffuse accumulation of amyloid protein in various anatomic sites. "Based on the fact that affected patients with amyloidosis also displayed hypotriglyceridemia and increased plasma levels of HDL-C as compared with non-carriers in the family, we next screened several candidate genes including the APOC3, APOC1, APOC2, APOC4, APOA4, APOA5 and APOE genes." (PMID 26790392, 2016).
aortic valve stenosis (1 paper, 2016). Aortic valve stenosis (AVS) is a condition characterized by narrowing of the heart's aortic valve opening. "Earlier association studies were conducted to examine the links between high-density lipoprotein genetics of various genes, including the APOA5 gene, and aortic valve stenosis risk." (PMID 27152866, 2016).
atrial fibrillation (1 paper, 2023). A disorder characterized by an electrocardiographic finding of a supraventricular arrhythmia characterized by the replacement of consistent P waves by rapid oscillations or fibrillatory waves that vary in size, shape and timing and are accompanied by an irregular ventricular response. "On the contrary, an increase in APOA5 expression is protective against atrial fibrillation, HDL, MI, and total cholesterol but becomes a risk factor for LDL." (PMID 38065874, 2023).
cerebrovascular disease (1 paper, 2025). "Although the roles of ABCA1 and APOA5 in lipid regulation are well-documented, their specific interactions with dietary components in modulating cardio-cerebrovascular disease risk remain underexplored." (PMID 40077648, 2025).
colon cancer (1 paper, 2024). "Further analysis was performed on the underlying correlation of APOA5 in L-OHP resistance of PIK3CA-E545K mutant colon cancer." (PMID 38848145, 2024). "Further correlation analysis of APOA5 expression and clinicopathological features indicated a higher percentage of APOA5 expression in right-sided colon cancer than the left (p = 0.015." (PMID 38848145, 2024).
colorectal cancer (1 paper, 2024). A primary or metastatic malignant neoplasm that affects the colon or rectum. "Univariate and multivariate analyses of APOA5 expression in disease-free survival and overall survival of 416 colorectal cancer patients." (PMID 38848145, 2024).
coronary stenosis (1 paper, 2022). Narrowing of the coronary artery lumen diameter. "The SNP rs662799 of APOA5 significantly increased the risk of having coronary stenosis ≥70% (adjusted OR 3.263 95% CI 1.406–7.569, p = 0.0059), but not that of having CACS ≥400." (PMID 35174233, 2022). "Among other SNPs, APOA5 rs2266788 and PXDNL s80056520 showed significant associations with CAC ≥400 and coronary artery stenosis ≥70%." (PMID 35174233, 2022). "The APOA5 rs662799 SNP was a significant determinant of LDL-C variability and also associated with significant coronary artery stenosis." (PMID 35174233, 2022). "Two SNPs associated with LDL-C variability (APOA5 rs662799 and rs2266788) and one SNP associated with HDL-C variability (PXDNL rs80056520) were significantly associated with advanced coronary artery stenosis." (PMID 35174233, 2022).
diabetic nephropathy (1 paper, 2022). "The association of this APOA5 polymorphism with diabetic nephropathy was also reported in a study of Egyptian patients." (PMID 36071387, 2022).
GI dysfunctions (1 paper, 2020). "In our study, serum ApoA5 levels could not be affected by age, gender, body weight, and pathogens, and it was specifically related the liver, kidney, and GI dysfunctions." (PMID 32322166, 2020).
hepatoblastoma (1 paper, 2022). Hepatoblastoma (HB) is a malignant hepatic tumor and is the most common pediatric liver cancer. "APOA5 is expressed solely in liver tissue, and therefore it was anticipated that experiments carried out with the liver cell line HepG2 (derived from a young hepatoblastoma with high-level APOA5 expression) would yield physiologically relevant results." (PMID 35046404, 2022).
ischemia (1 paper, 2021). A hypoperfusion of the BLOOD through an organ or tissue caused by a PATHOLOGIC CONSTRICTION or obstruction of its BLOOD VESSELS, or an absence of BLOOD CIRCULATION. "Here, by an initial manual query, the expression levels of the following six proteins associated with the PPAR signaling cascade were found to be significantly altered after hepatic ischemia/reperfusion: SCD, Perilipin, FABP, ACS, APOA5 and PEPCK." (PMID 33407080, 2021).
liver cancer (1 paper, 2024). An epithelial or non-epithelial malignant neoplasm that arises from the liver. "The identified connections with key lipid/triglyceride metabolism biomarkers, namely PPARA, APOC3, and APOA5, suggest the involvement of SELENOP in lipid homeostasis within the context of liver cancer." (PMID 39001444, 2024).
liver fibrosis (1 paper, 2024). "Additionally, oil red O staining and the quantitative data demonstrated that hepatic lipids, including TG and TC, were largely deposited in the livers, together with obvious liver fibrosis of ApoA5-/- hamsters." (PMID 38505614, 2024).
melanoma (1 paper, 2021). A malignant, usually aggressive tumor composed of atypical, neoplastic melanocytes. "By proteomics we identified five proteins in plasma CD81sEV that were differentially expressed between HD and stage II (APOA5, PON1, PON3 and CD14) and between HD and stage III–IV, advanced stage melanoma, (RAP1B)." (PMID 34439311, 2021). "To explore whether the identified proteins, APOA5, PON1, PON3, CD14 and RAP1B, could be of any clinical relevance, we evaluated their expression in silico in relation to the available clinical information in the TCGA dataset of primary melanoma samples (PM, n = 80)." (PMID 34439311, 2021).
meningitis (1 paper, 2023). A disorder characterized by acute inflammation of the meninges of the brain and/or spinal cord. "Here, we report APOA5 to be associated with meningitis, while previous studies implicated various other apolipoproteins, such as APOA1 and APOE, are involved in meningitis, as well as various bacterial or respiratory infections, both in human and mouse studies." (PMID 37108169, 2023).
metastatic melanoma (1 paper, 2021). A melanoma that has spread from its primary site to another anatomic site. "To explore the clinical relevance of APOA5 and PON1 as well, we selected a dataset containing RNA-seq data from circulating plasma-derived EV of metastatic melanoma patients." (PMID 34439311, 2021).
osteonecrosis (1 paper, 2014). A none disease characterized by death of bone tissue due to a lack of blood supply. "We designed a case–control study including 223 patients of osteonecrosis and 201 age- and sex-matched control subjects to analyze the association between ApoA5 polymorphisms and susceptibility of steroid-induced ONFH." (PMID 25515090, 2014).
osteonecrosis of femoral head (1 paper, 2014). "Therefore, genetic polymorphisms in ApoA5 may be associated with the occurrence of osteonecrosis of femoral head (ONFH)." (PMID 25515090, 2014).
prostate carcinoma (1 paper, 2021). A carcinoma that arises from epithelial cells of the prostate gland. "Moreover, APOA5 on 11q23.3 is significantly related to prostate cancer risk." (PMID 33737947, 2021).
respiratory failure (1 paper, 2020). The significant impairment of gas exchange within the lungs resulting in hypoxia, hypercarbia, or both, to the extent that organ tissue perfusion is severely compromised. "The serum levels of ApoA5 were decreased in patients with MODS (P < 0.001), shock (P = 0.002), AKI (P < 0.001), ALI (P = 0.002), or gastrointestinal (GI) dysfunction (P = 0.012), but not in patients with respiratory failure (RF) (P = 0.091), brain injury (P = 0.790)." (PMID 32322166, 2020).
thrombophilia (1 paper, 2023). A condition characterized by an abnormally high level of thrombi. "CD320, RTEL1, UCP2, APOA5 and PROZ participate in healthy-specific or disease-specific subnetworks involving thrombophilia-annotated genes and are related to general thrombophilia mechanisms according to the literature." (PMID 37098010, 2023).